RNU1-88P (RNA, U1 small nuclear 88, pseudogene)
Gene: Small nuclear RNA gene on chromosome 6 (36,639,545 to 36,639,672, reverse strand). Ensembl gene ENSG00000238554.
Homologues: Orthologues: chimpanzee U1 (99% identical), macaque U1 (95% identical), dog U1 (88% identical), pig U1 (87% identical), rabbit U1 (78% identical), mouse Gm25280 (62% identical). Paralogues in human: RNU1-1 (89% identical), RNU1-2 (89% identical), RNU1-27P (89% identical), RNU1-28P (89% identical), RNU1-3 (89% identical), RNU1-4 (89% identical), RNVU1-18 (89% identical), RNVU1-29 (89% identical), RNVU1-7 (89% identical), U1 (89% identical), RNVU1-28 (88% identical), RNU1-89P (88% identical), and 133 more.